ICAM1 (intercellular adhesion molecule 1)
Diseases named in the same sentence as ICAM1 in open-access papers (continued):
Sharing a sentence is not in itself a finding about the gene and the disease.
glioma (continued). "Studies have shown that NSUN2 can increase the stability of LINC00324 by regulating m5C modification, thereby regulating glioma angiogenesis, and can also enhance the translation of intercellular adhesion molecule 1 (ICAM-1) to reduce inflammatory responses in the vascular endothelium." (PMID 38764010, 2024). "Similarly, DAC-induced upregulation of ICAM1 has been reported in several cancer cell lines, including cutaneous melanoma, pediatric sarcoma, and glioma cells." (PMID 36776856, 2023). "Additionally, miR-222 has been shown to regulate ICAM1 in glioma cells, highlighting its potential role in modulating ICAM1 expression." (PMID 37653173, 2023). "In parallel, glioma-associated macrophages are stimulated by glioma cells to produce tumor necrosis factor-α (TNFα), which activates the endothelial cell expression of the proangiogenic molecules (VCAM-1, ICAM-1, CXCL5, and CXCL10)." (PMID 35740307, 2022). "Moreover, intercellular adhesion molecule 1 (ICAM1) silencing in the IDH1 wild-type glioma cells is demonstrated to increase macrophage infiltration and potentially enhance anti-tumor functions like phagocytosis." (PMID 34671362, 2021). "It has been shown that inhibition of ICAM-1 reduced glioma invasion in vitro and in vivo." (PMID 34207434, 2021). "We analyzed SIRT1, CCL2, VCAM-1 and ICAM-1 in human glioma cell lines by immunoblotting." (PMID 31207928, 2019). "To test this hypothesis, we investigated the regulation of ICAM-1 expression in bevacizumab-treated glioma stem cells (GSCs) in vitro and in in vivo murine glioma models." (PMID 29228586, 2017). "To determine whether ICAM-1 could serve as a therapeutic target in glioblastoma, we used five independent shRNAs to stably knock down ICAM-1 expression in GSC11 glioma stem cells." (PMID 29228586, 2017). "Importantly, ICAM-1 is markedly expressed in many different types of human cancer cells, including lung, pancreatic, breast, and prostate cancer cells, as well as in glioma." (PMID 29228586, 2017). "We performed Western blotting to determine whether ICAM-1 is expressed in a panel of glioma stem cells." (PMID 29228586, 2017). "However we also found that after treated with bevacizumab, glioma cells with ICAM-1 knockdown were less invasive than bevacizumab-treated parental glioma cells." (PMID 29228586, 2017). "We also detected ICAM1 expression in most glioma stem cells (GSCs)." (PMID 29228586, 2017). "In addition, a higher level of ICAM-1 mRNA expression was also observed in glioma samples classified as high grade." (PMID 26473373, 2015). "Therefore, we hypothesized that hypoxia inducible factor-1α (HIF-1α) up-regulates ICAM-1 expression in glioma cells." (PMID 29228586, 2017). "Interestingly, recent work has shown that miR-222 can regulate ICAM1 in glioma cells." (PMID 22535415, 2012). "The effects of serotonergic neurons on glioma cells are mediated by both known (e.g. NLGN3) and previously underappreciated growth factors such as ICAM-1 and NCAM-1, and through activation of the serotonin receptor HTR2A." (PMID 41427306, 2025). "To investigate the association between PLAUR in macrophages and the mediation of MES transition in glioma cells with OSM or ICAM1, we assessed the mRNA expression of OSM and ICAM1 in THP1-derived macrophages following lentiviral shPLAUR or shNT transfection." (PMID 38398231, 2024). "It was observed that TAM cells with high PLAUR expression exhibited increased levels of ICAM-1, OSM, and other molecules known to mediate the MES phenotype of glioma." (PMID 38398231, 2024). "Let-7 miRNA directly activates TLR7 in microglia, leading to upregulation of MHC I and ICAM1 (CD54) and induction of TNF-α production to inhibit glioma growth." (PMID 37700840, 2023). "In our study, we found that the expression of VCAM1, ICAM1, CDH2 was down-regulated, while the expression of SDC2 was up-regulated after knocking down the expression of GNG5 in glioma cells." (PMID 34098960, 2021).
glioma (continued). "In the present study, we found that inhibiting ICAM-1 expression reduced glioma invasion in vivo and in vitro, suggesting a potentially important role for ICAM-1 in glioma invasion." (PMID 29228586, 2017). "We confirmed this result using GSC17 glioma stem cells (as GSC17 cells have a lower baseline ICAM1 expression level) and found that the ICAM-1 expression level was also increased under hypoxic conditions or after CoCl2 treatment in these cells." (PMID 29228586, 2017). "Next, we used GFP-tagged ICAM-1 shRNA lentivirus to knock down ICAM-1 in GSC11 and GSC17 glioma cell lines." (PMID 29228586, 2017). "Glioma tumors were embedded in paraffin block, and subjected to co-immunofluorescence staining for HIF-1α and ICAM-1." (PMID 29228586, 2017). "DAC treatment of glioma cells was tested for its impact on the expression of selected surface molecules (i.e. MHCI and ICAM-1) considered important for CTL-target cell binding." (PMID 27579489, 2016). "Our data suggest IFN-β increased ICAM1 and VCAM1 directly or indirectly through inhibition of VEGF production with glioma cells, resulting reversal of leukocyte adhesion." (PMID 25175315, 2014). "Moreover, we observed also an increasing level of ICAM-1 and VCAM-1, strongly related to glioma clinico-pathological grade." (PMID 41029387, 2025). "We found that decreasing the expression level of GNG5 in glioma cells could significantly affect the expression of VCAM1, ICAM1, CDH2, and SDC2, which are key molecules of cell adhesion molecules." (PMID 34098960, 2021). "GSE4290 indicated that VCAM-1 and ICAM-1 levels were higher in the grade four glioma group than in the low-grade glioma and non-tumor group." (PMID 31207928, 2019). "In addition to NCAMs, intercellular adhesion molecule-1 (ICAM1), a member of the immunoglobulin family of genes and expressed in several cell types, has recently been shown to contribute to glioma cell invasion." (PMID 31467533, 2019). "Such an approach is supported by previous studies which have shown that vaccination with ICAM-1–transfected tumor cells markedly inhibited the growth of subcutaneously inoculated glioma but not glioma located in the brain." (PMID 29228586, 2017). "Previous studies have shown that ICAM-1 is highly expressed in glioblastoma, only weakly expressed or absent in low-grade glioma, and undetectable in normal and fetal brain." (PMID 29228586, 2017). "Furthermore, TMEM140 knockdown remarkably decreased the protein levels of ICAM1, VCAM1, and Syndecan1, which are considered to be important in glioma cell migration and invasion." (PMID 26198430, 2015). "By flow cytometry, the IL13Rα2-positive glioma cell lines (PBT015, PBT017-4, PBT030, PBT036, U251T) generally express higher levels of the mesenchymal adhesion markers CD44 and CD54/ICAM-1 than the IL13Rα2-negative glioma lines (PBT003-4, PBT008, PBT009, PBT022)." (PMID 24204956, 2013). "Furthermore, ICAM-1 and VCAM-1 play important roles in the adhesion of cancer cells to the endothelium, especially in the context of the inflammatory microenvironment, supported by the high concentration of IL-1b, correlated with higher grade gliomas." (PMID 35741603, 2022). "Considering malignant glioma cells and HCT8 cells are both cancer cells, we suppose that some factor(s) present in HPMECs but absent in cancer cells may compensate for the lack of HuR in regulating IL-8 but not ICAM-1 after TNF-α stimulation." (PMID 27215284, 2016).
myeloma (50 papers, 1993 to 2026). "ICAM-1 is an adhesion molecule highly expressed on myeloma cells and associated with drug-resistance in patients." (PMID 35784366, 2022). "More specifically, VLA-4, which binds to VCAM-1 or fibronectin, and LFA (leucocyte function associated antigen)-1, which binds to ICAM-1, bring myeloma cells in contact with BMSCs, respectively." (PMID 33923357, 2021). "Adhesion molecules like ICAM-1 on multiple myeloma cells increase the binding capacity to BMSCs and overexpression of ICAM-1 have been associated with more advanced disease and drug resistance." (PMID 28158311, 2017). "Also in the intercellular adhesion molecule (ICAM) family, myeloma-associated ICAM1 was upregulated in the KO MM clones." (PMID 34996933, 2022). "A CRISPR-based screen in a multiple myeloma cell line revealed that knockout of the ICAM-1 gene in tumor cells led to resistance to B-cell maturation antigen (BCMA) CAR T cells." (PMID 39911389, 2025). "On top of that, combining elotuzumab with lenalidomide significantly increased ICAM-1 expression in both NK cells and multiple myeloma cells, surpassing the effects of either treatment alone." (PMID 39911389, 2025). "BI-505, a human anti-ICAM-1 monoclonal antibody, was evaluated in multiple myeloma patients (NCT01025206), and it demonstrated good tolerability, along with efficacy in 7 of 29 patients who had stable disease for at least 8 weeks." (PMID 39482533, 2024). "ICAM-1 conjugated with a cytotoxic drug was extensively tested for multiple myeloma and another bispecific anti-CD38-ICAM-1 drug for multiple myeloma is under development." (PMID 37006265, 2023). "Myeloma cells express high levels of very late antigen-4 (VLA-4)/integrin α4β1 that binds to its receptor ICAM-1 expressed on endothelial cells." (PMID 37744361, 2023). "The VLA-4/ICAM-1 interaction enables myeloma cell adhesion to the vessel wall followed by trans-endothelial migration and engraftment." (PMID 37744361, 2023). "Naked anti-ICAM1 antibodies were active in preclinical studies and safe in myeloma patients but showed limited clinical efficacy; thus, an anti-ICAM1 ADC was developed for better targeting MM cells." (PMID 35466275, 2022). "Veitonmäki and colleagues identified an ICAM-1 antibody (BI-505) using cellular panning of a human phage antibody library, which was tested in a phase 1 trial for myeloma therapy." (PMID 35784366, 2022). "GGT1, ICAM3/CD50, and ICAM1/CD54, earlier identified in the myeloma cell line proteomics, were among the most enriched proteins on the primary myeloma cell surface relative to B-cells." (PMID 35840578, 2022). "In previous works, we already identified an intercellular adhesion molecule-1 (ICAM-1/CD54) antibody by cellular panning of the synthetic human Tomlinson library that had potent anti-myeloma activity in vitro and in vivo." (PMID 35784366, 2022). "Phage antibodies #5 and #23 bound to B and/or T cell lymphoma/leukemia cells and were identified as CD38 and ICAM-1 antibodies, respectively, by using stably transfected CHO cell lines expressing one out of 10 individual human myeloma-associated antigens." (PMID 35784366, 2022). "Treatment with IMiDs decreases the expression of vascular-cell-adhesion molecule 1 (VCAM-1) and intercellular adhesion molecule 1 (ICAM-1), which play key roles in the adhesion of multiple myeloma to the bone marrow compartment." (PMID 34638271, 2021). "Pharmacological inhibition or genetic knockdown of PSGL‐1 or ICAM‐1 signaling in these myeloma cells can diminish the protective effects of TAMs from cytotoxic cancer‐killing agents including melphalan, doxorubicin, and bortezomib." (PMID 33463063, 2021). "For instance, a direct physical interaction involving E/P selectins and CD18 on macrophages and P-selectin glycoprotein ligand 1 (PSGL-1) and intercellular adhesion molecule-1 (ICAM-1) on myeloma cells protects plasma cells from drug-induced apoptosis." (PMID 33194767, 2020).
myeloma (continued). "More recently, an antibody against ICAM-1 was developed for its cytotoxic activity against multiple myeloma cells, which appeared to be mediated by antibody-dependent cell cytotoxicity." (PMID 31337787, 2019). "In myeloma, overexpression of ICAM-1 was negatively correlated with patient survival, and ICAM-1-CD18 interactions seem to be involved in macrophage-induced drug resistance." (PMID 29100408, 2017). "Since several independent observations indicate that ICAM-1 is highly expressed and involved in the pathogenesis of myeloma, it constitutes an attractive novel target for immunotherapy of multiple myeloma." (PMID 28158311, 2017). "The first human anti-ICAM-1 IgG1 mAb BI-505 was recently evaluated in clinical trials for patients with relapsed/refractory MM and smoldering myeloma." (PMID 29100408, 2017). "It has been shown a clinical correlation between the increased levels of circulating ICAM-1 and myeloma progression in untreated patients." (PMID 28702457, 2017). "It was recently reported that immunotherapy targeting ICAM1 is effective in treating multiple myeloma." (PMID 25879517, 2015). "Moreover, ICAM1 has been reported to be upregulated in multiple myeloma cells in comparison with normal cells." (PMID 38054018, 2023). "Myeloma cell adhesion to BMSCs or extracellular matrix components by expression of adhesion molecules such as Syndecan-1, intercellular adhesion molecule 1 (ICAM-1) or vascular cell adhesion protein 1 (VCAM-1) prevent apoptosis, resulting in cell-adhesion driven drug resistance." (PMID 37744361, 2023). "In previous own work, we were able to show that Fc-engineering of an ICAM-1 antibody isolated from a synthetic human scFv antibody library markedly enhanced the antibody’s anti-myeloma activity in vitro and in vivo most likely by improving the recruitment of immune cells." (PMID 35784366, 2022). "Interestingly, in this work we again isolated a novel ICAM-1 antibody (#23) from our immune library, but further investigation is needed to unravel the antibody’s characteristics and its potential for myeloma therapy." (PMID 35784366, 2022). "Potent anti-myeloma cytotoxicity was displayed by anti-ICAM1 ADC in vitro and in vivo." (PMID 35466275, 2022). "Using stably transfected Chinese hamster ovary cells expressing individual myeloma-associated antigens revealed that two antibodies bind CD38 and intercellular adhesion molecule-1 (ICAM-1), respectively, and 7 antibodies target yet unknown antigens." (PMID 35784366, 2022). "The interaction of very late antigen 4 (VLA-4), vascular adhesion molecule (VCAM), leukocyte function-associated antigen 1 (LFA-1), and intercellular adhesion molecule 1 (ICAM-1) with bone marrow stromal cells induces primary multidrug resistance in vitro and in vivo in multiple myeloma cells." (PMID 34502361, 2021). "Retrospective analysis of bone marrow samples obtained from this trial revealed increased infiltration of CD56dimCD16+ NK cells exhibiting higher expression of the adhesion molecule, CD54 (ICAM-1), and concomitant reduction in CD45dimCD138+ myeloma cells at cycle 1 day 22, as compared to baseline." (PMID 30455698, 2018). "One recent study also demonstrated that the BI-505 antibody, an anti–human ICAM-1 antibody, could specifically target B-cell tumors and had broad anti-myeloma activity in vivo by inducing programmed cell death." (PMID 29228586, 2017). "BI-505, a monoclonal antibody directed against intercellular adhesion molecule 1 (ICAM-1) with promising anti-myeloma activity in preclinical trials, is a possible treatment approach for this patient category with potential to eliminate tumor cells with minimal long-term side effects." (PMID 28158311, 2017). "In conclusion, by combining phage display, cellular panning and NGS analyses of an immune library, we successfully identified two novel CD38 and ICAM-1 antibodies, and at least 7 antibodies targeting yet unknown, potentially novel antigens on myeloma cell surface." (PMID 35784366, 2022).
myeloma (continued). "We analyzed the morphology of the patient primary myeloma cells for expression levels of MHC I, MICA, MICB, ULBP1, ULBP2/5/6, HLA-E, CD38 (n = 12), CD112, CD155, ICAM-1 and PD-L1 (n =5) using flow cytometry." (PMID 35413499, 2022). "Using a human peripheral blood lymphocytes (PBL)/myeloma co-culture model, the authors described the upregulation of IL-2Rα and CD54 (ICAM-1) expression on NK cells." (PMID 32899714, 2020). "In our study, we evaluated a large number of myeloma patients and found that patients with NDMM had higher levels of VCAM-1 and ICAM-1 compared with MGUS patients and higher VCAM-1 levels compared with SMM patients." (PMID 27232930, 2016). "In this study, we compared recombinant ICAM-1 expressed in HEK293 and COS-7 cells with mouse myeloma NS0 ICAM-1 purchased from a commercial vendor in terms of protein purity, yield, fold, ability to bind DBLβ, and relative cost." (PMID 23936131, 2013). "In this study, we compared ICAM-1 expression in HEK293, COS-7, and mouse myeloma NS0 cells, in terms of protein purity, yield, folding, the ability to bind a recombinant DC4-containing PfEMP1 protein, and relative cost." (PMID 23936131, 2013). "The anti-leukemic action of NK cells would also be strengthened by the ability of SUMOylation inhibition to induce the expression of NK-activating ligands at the surface of cancer cells, as we demonstrated for ICAM-1 on AML cells and as it was shown for PVR on Multiple Myeloma cells." (PMID 40661051, 2026). "Myeloma: PEDF decreases vascular endothelial growth factor (VEGF), monocyte chemoattractant protein-1 (MCP-1), intercellular cell adhesion molecule-1 (ICAM-1) and plasminogen activator inhibitor-1 (PAI-1) mRNA levels in myeloma cells, through its signalling via the laminin receptor (LR)." (PMID 40649783, 2025). "MSCs from myeloma patients (MM-MSCs) interrelate with MM cells and change the expression of certain angiogenic and growth factors (such as CD40/40L, VCAM-1, ICAM-1, LFA-3 and HO-1) and several cytokines (IL-6, IL-10 TGFb1, macrophage inflammatory protein-1b (MIP-1b) and IL-7)." (PMID 33923357, 2021). "In addition, we found that direct co-culture of hMSCs with two myeloma cell lines prior to and during adipogenic differentiation resulted in increased secretion of CXCL1/GRO, IL-8, and ICAM-1 in co-culture conditioned medium samples." (PMID 33680918, 2020). "Blockade of ICAM-1 also inhibited the phagocytosis of live T cell lymphoma (EL4) but not other cell types such as myeloma (NSO) by stimulated macrophages." (PMID 28733045, 2017). "The maximum tolerated dose was not reached up to 20 mg/kg while ICAM-1 epitopes on patients’ myeloma cells were saturated already at 10 mg/kg." (PMID 29100408, 2017). "Moreover, functional activation of the LFA-1–ICAM-1 pathway was observed in our model, with upregulation of ICAM-1 on both NK cells and myeloma cells apparent in treated cultures." (PMID 25287778, 2015). "Once these myeloma cells enter the bone marrow, they adhere to the bone marrow stromal cells through the interaction of CXCR4/stromal derived factor (SDF)-1, VLA-4/VCAM-1, LFA-1/ICAM-1, or others." (PMID 24252328, 2013). "Soluble ICAM-1 and VCAM-1 levels were significantly higher in all the patient groups compared with the controls whereas soluble E-selectin was significantly higher in the ovarian, breast and GI cancer groups and lower in the myeloma group." (PMID 7686390, 1993). "Thus, pronounced toxicity of anti-ICAM-1 antibodies were not reported – suggesting a therapeutic window for TP15-Fc antibody therapy in myeloma." (PMID 29100408, 2017). "For instance, IFN-γ enhances ICAM-1–mediated CAR T-cell cytotoxicity against various types of solid tumor but not the leukemia, lymphoma, or myeloma CDX models, although this different IFN-γ sensitivities are unclear in clinical level." (PMID 36059449, 2022).